H3Y2 (H3.Y histone 2)
Description:
Primate-specific variant histone H3, which constitutes a core component of nucleosomes. Nucleosomes wrap and compact DNA into chromatin, limiting DNA accessibility to the cellular machineries which require DNA as a template. Histones thereby play a central role in transcription regulation, DNA repair, DNA replication and chromosomal stability. DNA accessibility is regulated via a complex set of post-translational modifications of histones, also called histone code, and nucleosome remodeling (Probable).
Synonyms: H3.X; H3.Y.2
Tractability: No criterion of Open Targets' tractability assessment is met for any kind of drug.
Gene: Protein-coding gene on chromosome 5 (17,490,967 to 17,492,076, reverse strand). Ensembl gene ENSG00000268799.
Subcellular location: Nucleus; Chromosome
Subcellular location (Human Protein Atlas): Nucleoplasm
Gene Ontology:
Molecular function: nucleosomal DNA binding; structural constituent of chromatin; DNA binding; protein heterodimerization activity
Biological process: heterochromatin formation; kinetochore assembly; mitotic metaphase chromosome alignment
Cellular component: nucleoplasm; nucleosome; nucleus; kinetochore; chromosome
Homologues: Orthologues: Drosophila melanogaster His3.3A (76% identical), Drosophila melanogaster His3.3B (76% identical), guinea pig H3-5 (76% identical), mouse H3f3b (76% identical), pig H3-3A (76% identical), rat H3f3b (76% identical), zebrafish h3f3a (76% identical), zebrafish si:ch1073-429i10.3 (76% identical), Caenorhabditis elegans his-74 (75% identical), Caenorhabditis elegans his-70 (67% identical), Caenorhabditis elegans his-69 (65% identical), rat H3f3bl1 (37% identical). Paralogues in human: H3Y1 (90% identical), H3-3A (76% identical), H3-3B (76% identical), H3C13 (73% identical), H3C14 (73% identical), H3C15 (73% identical), H3-5 (73% identical), H3C1 (73% identical), H3C10 (73% identical), H3C11 (73% identical), H3C12 (73% identical), H3C2 (73% identical), and 8 more.
Diseases named in the same sentence as H3Y2 in open-access papers:
H3Y2 is named in the same sentence as 1 disease in open-access papers, as found by Europe PMC text mining. Sharing a sentence is not in itself a finding about the gene and the disease. The quoted sentences say what the papers report.
viral infection (1 paper, 2023). "The role of MAK16 and H3Y2 in viral infection is unclear, while RBMX, which encodes X-ed RNA binding motif proteins, responds to SARS-CoV-2 entry via viral RNA-host protein interactions." (PMID 36690780, 2023).